MIR29B1 (microRNA 29b-1)
Synonyms: hsa-mir-29b-1; MIRN29B1; miR-29b; miRNA29B1; mir-29b-1
Gene: MicroRNA gene on chromosome 7 (130,877,459 to 130,877,539, reverse strand). Ensembl gene ENSG00000283797.
Gene Ontology:
Biological process: miRNA-mediated post-transcriptional gene silencing
Cellular component: RISC complex
Homologues: Orthologues: chimpanzee ptr-mir-29b-1 (100% identical), macaque mml-mir-29b-1 (100% identical), pig ssc-mir-29b-1 (99% identical), rabbit MIR29B1 (96% identical), guinea pig MIR29B1 (88% identical), mouse Mir29b-1 (88% identical), tropical clawed frog xtr-mir-29d (79% identical). Paralogues in human: MIR29B2 (80% identical), MIR29C (58% identical), MIR29A (56% identical).